HIF1A (hypoxia inducible factor 1 subunit alpha)
Diseases named in the same sentence as HIF1A in open-access papers (continued):
Sharing a sentence is not in itself a finding about the gene and the disease.
tumor (continued). "In contrast, the median transcript ratios of the 19 adjacent non-tumor tissues were 0.2 copies HIF-1α mRNA per HPRT mRNA copy (ranging from 0–1.6; mean 0.3) and 0.06 copies EGFR mRNA per HPRT mRNA copy (range 0–0.3, mean 0.07)." (PMID 30513863, 2018). "The problem with the use of anti-vascular drugs is the stimulation of necrosis around the damaged blood vessels and an increase of hypoxia areas in tumor that leads to HIF-1α transcription factor activation." (PMID 29743548, 2018). "Immunoblotting of tumor tissues also showed similar patterns in the expression of HIF-1α, HIF-2α, VEGF, pro-caspase-9, pro-caspase-3 and cleaved PARP, compared with the in vitro results." (PMID 29946188, 2018). "In this context, in a model of NKp46-targeted HIF1α KO mice, it has been recently shown that NK cells can reach hypoxic tumor tissues, influence angiogenesis, tumor growth, and metastasis spread in a HIF1α-dependent fashion." (PMID 30459756, 2018). "High HIF1α expression leads to increased proliferation and invasion of tumour cells as well as inducing expression of genes involved in EMT, such as vimentin, VEGF and E-cadherin." (PMID 29844410, 2018). "The present study revealed the potential role of PHD-2 activators in curtailing the growth of tumor cells by down-regulating the level of HIF-1α and FASN." (PMID 35541235, 2018). "A high expression of HIF-1α upregulates the expression of VEGF, while upregulation of HIF-1α expression can promote the formation of tumor angiogenesis." (PMID 29531823, 2018). "Stem cell antigens were expressed in dividing cells, while hypoxia inducible factor-α (HIF-1α) is expressed in all tumor cells." (PMID 30424475, 2018). "While HIF1α can act as a ccRCC tumor suppressor, HIF2α has emerged as the key HIF isoform that is essential for ccRCC tumor progression." (PMID 29938199, 2018). "We found that the combined treatment reduced the HIF-1α protein levels and collagen deposition in tumor tissue." (PMID 30367042, 2018). "Taken together, our data demonstrates that high levels of ∆Np73 stabilize HIF-1α protein, allowing for it to accumulate and further potentiating its transcriptional activity and supporting tumor progression." (PMID 29628507, 2018). "Clinically, serum VEGF is elevated in patients with ES, which correlates strongly with expression of HIF1-α in the primary tumour." (PMID 29098360, 2018). "This reference time course allowed us to next focus on the dynamic changes of TF motifs, which we assume to be involved in hypoxic responses of tumor cells, because they are enriched in HIF1α high group in the Pi-ATAC tumor experiment." (PMID 30389926, 2018). "Most likely an up regulation of IGFBP-2 mirrors the hypoxic state of the tumor through HIF-1α, a master transcriptional regulator of the hypoxic response." (PMID 30592740, 2018). "Hypoxia inducible factor 1α (HIF-1α) can transcriptionally upregulate LDH-A in tumor cells to ensure anaerobic glycolysis and produce enough lactate." (PMID 30627541, 2018). "IHC staining of sections of tumor xenografts showed that upregulation of BART1-5P significantly reduced the expression of AMPKα1 but increased HIF-1α, GLUT1, LDHA and mTOR when compared with the relative control." (PMID 30557400, 2018). "In hypovascularized tumor areas, hypoxia induces HIF-1α production, which intensifies anaerobic glycolysis and lactate production, suppresses the immune response, and induces invasion and metastasis." (PMID 29695779, 2018). "HIF-1α is an important transcription factor for responding to hypoxia, and plays an important role in tumor metastasis." (PMID 29433520, 2018). "The phenomenon is mostly due to the HIF-1α-driven increased arginase activity and nitric oxide production of tumor MDSCs." (PMID 30061885, 2018).
tumor (continued). "In tumor cells, high glucose levels promote HIF-1α expression under both normoxic and hypoxic conditions." (PMID 30455857, 2018). "Elaiophylin downregulated the expression of VEGF by inhibiting hypoxia inducible factor-1α (HIF-1α) accumulation in tumor cells." (PMID 29498688, 2018). "Many recent studies have provided evidence of strong correlation between HIF-1α and its target genes with tumor resistance, metastasis, angiogenesis, poor prognosis, etc.." (PMID 30246018, 2018). "Given that both VEGFR2 and HIF-1α are key regulators of tumor angiogenic processes, dual targeting of the two angiogenic pathway axes would provide more effective therapeutic potential for the treatment of hypervascularized tumors." (PMID 29498688, 2018). "Beside regulation of immunosuppressive MDSCs and Tregs within the tumor, recent studies showed that hypoxia promotes immune evasion through HIF-1α-dependent upregulation of immune checkpoint proteins in tumors." (PMID 30061885, 2018). "Our investigations have shown that levels of VEGF-A are higher in tumor cells expressing HIF1α than in cells expressing HIF2α." (PMID 29535842, 2018). "For C90 tumor, the expression of only two genes, namely Pai1 and Plau, were significantly increased, while Hif1a and Fn1 genes were significantly decreased compared with that of G0 tumor." (PMID 29362374, 2018). "HIF-1α expression, mediated by ROS generation, plays a central role in the inflammatory tumor microenvironment." (PMID 29435131, 2018). "The cell surface factor CD24 has been shown to be an effector of HIF-1α driven primary tumor growth and metastasis." (PMID 29552303, 2018). "The reduction in oxygen tension that characterizes proliferating tumor tissues, stimulates the hypoxia-inducible factor α (HIF1α), which drives the anaerobic glycolysis." (PMID 30466459, 2018). "We identify a dominant role for hypoxia, marked by HIF1α protein, in the tumor microvenvironment for shaping the regulome in a subset of epithelial tumor cells." (PMID 30389926, 2018). "PKM2 can also enhance tumor angiogenesis by interacting with NF-κB and HIF-1α in the nucleus and activating the expression of HIF-1α target gene VEGF-A." (PMID 29455645, 2018). "Under hypoxic conditions, HIF-1α in tumor cells, bone marrow-derived suppressor cells, and dendritic cells promotes the expression of downstream PD-L1 by acting on HREs." (PMID 30477520, 2018). "The hypoxic environment of the primary tumor induces the stabilization of HIF-1α and shutdown of the TCA cycle, but newly developing pulmonary metastases lose HIF-1α expression." (PMID 30005601, 2018). "In HIF-1α-deficient tumors, ectopic PLOD2 expression restores the migration and metastatic potential, and inhibition of PLOD2 activity suppresses the tumor metastases." (PMID 30003082, 2018). "We provided evidence that hypoxia increased the MMP-13 levels in tumor-derived exosomes in a HIF-1α-dependent manner." (PMID 29515112, 2018). "In conclusion, our data demonstrate that tumor cell death induced by TSA is inhibited by HIF-1α acetylation, its nuclear translocation and binding to the HRE of the VEGF promoter." (PMID 29416751, 2018). "HIF-1α inactivation in Tie2-positive ECs drastically decreased lung metastasis, but only had moderate effect on primary tumor growth." (PMID 29896451, 2018).
tumor (continued). "The hypoxic adaption mediated by the master transcriptional regulator, HIF-1α, is the best characterized metabolic alteration, which mediates the survival of tumour cells to survive by aerobic glycolysis reprogramming." (PMID 29476053, 2018). "Tumour cell growth further promotes the enrichment of HIF1α in tumour cells, which forms a feedback loop in the tumour cell microenvironment." (PMID 29472550, 2018). "Expression level of HIF-1α mRNA was significantly increased in tumor tissues compared with adjacent healthy tissues in 52 out of 58 patients." (PMID 29899167, 2018). "Our results showed that tumor hypoxia at molecular level was relatively high at early stage of tumor development as reflected by initially high HIF1A and VEGFA expression levels and their subsequent decrease." (PMID 30412628, 2018). "HIF-1 consists of two subunits: HIF-1β: a constitutively expressed subunit; and HIF-1α, an activity-determining unit that regulates tumor metabolism, proliferation and metastasis." (PMID 30258464, 2018). "Hyperactivation of the major Pro‐survival signaling kinases Akt and mTOR is present in several types of tumors including RCC, and overexpression of HIF‐1α and HIF‐2α is linked to tumor progression of RCC." (PMID 30107094, 2018). "Strong CSRP2 signals were very frequently associated with HIF-1α positive regions in both MCF-7 and MDA-MB-231 tumour xenografts." (PMID 29976963, 2018). "Collectively, this study provided firm evidence that ALDOA was crucial in GC by inducing the EMT pathway and affecting HIF‐1α activity in tumour progression and metastasis." (PMID 29992789, 2018). "The role of HIF1α in controlling the expression of PKM2 is an outcome of hypoxic conditions that exists in tumor cells." (PMID 29844464, 2018). "To investigate the effect of ∆Np73 on HIF-1α levels in vivo, in an established tumor, we injected E1A/Ras-transformed wild-type and ΔNp73 knockout MEFs in Nude mice and followed tumor growth." (PMID 29628507, 2018). "Other factors in the tumor microenvironment, such as poor oxygen perfusion can also contribute to elevated levels of HIF-1α, thereby compounding the cellular response to radiation." (PMID 29891977, 2018). "The lung tissues with tumor metastasis were analyzed for markers of oxidative stress and inflammation and for HIF-1α using western blotting and real-time PCR (qRT-PCR)." (PMID 29433520, 2018). "In ES, tumour cells that line blood lakes were shown to express HIF-1α which co-localised with the hypoxia marker pimonidazole in conjunction with vasculogenic mimicry." (PMID 29098360, 2018). "The levels of the HIF-1α subunit can increase rapidly in response to hypoxia, in turn upregulating factors that are important for tumor expansion." (PMID 29135410, 2018). "The GTP-bound active form of Ras homolog enriched in brain (Rheb) interacts and activates mTORC1, which drives VEGF secretion in tumor cells by inducing HIF-1α, promoting fragile tumor vessels." (PMID 30214642, 2018). "In conclusion, we provided evidence that hypoxia increased the MMP-13 levels in tumor-derived exosomes in a HIF-1α-dependent manner." (PMID 29515112, 2018). "In astrocytes, where HIF-1α appears to have tumour-suppressor effects, d-2-HG production has clearly been shown to stimulate PHD2-mediated degradation of HIF, enhancing cell proliferation." (PMID 29772792, 2018). "HIF-1 activity in tumors depends on the availability of HIF-1α subunit, the expression of which increases under hypoxic conditions and through the activation of oncogenes and/or inactivation of tumor suppressor genes." (PMID 29498688, 2018). "In subcutaneous lung and gastric xenograft tumors on the other hand, HIF-1α knockdown stimulated tumor growth." (PMID 30420794, 2018). "Induction of HIF-1α in tumor cells activates the angiogenic switch and allows for metabolic adaptations." (PMID 29628507, 2018).
tumor (continued). "The fact that HIF1α protein levels and its target genes were elevated in the pre-tumor stage (6 months) implies that these metabolic changes fuel and drive HCC development in DEN-treated WwoxΔHep mice." (PMID 29724996, 2018). "Supporting these observations, pro-inflammatory cytokines are known to induce HIF-1α expression in normoxia, nevertheless cytokine-dependent effects are also observed in the hypoxic inflammatory tumor microenvironment." (PMID 29996493, 2018). "We first analysed the expression level of HIF‐1α, which resulted up‐regulated in AQP1 siRNA‐treated tumour, as expected, being AQP1 silencing associated with reduced tumour angiogenesis." (PMID 29044946, 2018). "HIF-1a expression was also detected in the subcutaneous tumour implants, including those generated by HCC cells alone, HCC cells with hepatic stellate cells, HCC-Mock cells alone, and HCC-TGM2 OE cells alone." (PMID 30393774, 2018). "On the other hand, it has been found that knockdown of HIF-1α in a human NSCLC cell line results in the restoration of cytotoxic T lymphocyte-mediated tumor cell lysis under hypoxic conditions." (PMID 30250643, 2018). "Our results also showed that the gene expression of Hif1a and its downstream target genes were increased in G180 tumor." (PMID 29362374, 2018). "MnO2 led to remarkable downregulation of HIF-1α, indicating tumor hypoxia was successfully relieved." (PMID 30127408, 2018). "The results indicated that the percentage of HIF-1α positive cells in tumor tissue was an independent factor for TMR value." (PMID 30246018, 2018). "Herein, we report that monocytes under IH, either from patients with OSA or from an IH in vitro model, produce VEGF in an HIF1α-dependent manner and subsequently induce enhanced tumor progression, as validated in a 3D in vitro tumor model." (PMID 29997451, 2018). "HIF1A functions to regulate cellular metabolism to overcome hypoxia, while hypoxia promotes apoptosis in both normal and tumor cells." (PMID 30233638, 2018). "The expression levels of HIF-1α and miR-26a in tumor tissues were analyzed by immunohistochemistry and in situ hybridization, respectively, which were consistent with previous results." (PMID 30425242, 2018). "Low oxygen levels inside the tumor stimulate expression of hypoxia-inducible factor 1α (HIF1A) transcription factor which regulates expression of more than 100 other genes." (PMID 30412628, 2018). "Several mechanisms have been analyzed by which HIF-1α regulates the fate and function of MDSCs in a hypoxic tumor environment." (PMID 30425715, 2018). "In this study, 26 of 49 patients had high HIF1α and HIF2α expression on the tumor cells (based on immunoblot analysis)." (PMID 30513765, 2018). "Lactic acid, an end product of both aerobic and anaerobic glycolysis, activates vascular endothelial growth factor (VEGF), transforming growth factor β (TGF-β), and HIF-1α in oxidative tumor cells." (PMID 30619850, 2018). "NF-κB and HIF-1 are related to both gene and protein levels, and it has been suggested that activation of NF-κB and HIF-1α can promote angiogenesis or tumor progression." (PMID 29531823, 2018). "WWOX has been shown to act as a tumor suppressor modulating cellular metabolism via regulating hypoxia-inducible factor 1α (HIF-1α) levels and function." (PMID 29724996, 2018). "This immunosuppressive role of HIF1α is also supported by tumor studies, in which this factor was crucial to polarizing tumor-associated macrophages toward a tumor-promoting phenotype." (PMID 29997451, 2018). "In cancer, HIF-1 activation is associated with expression of CD69 (a marker of activated T cells) on cytotoxic T lymphocytes (CTLs) in hypoxic regions of tumour, suggesting a pro-tumour killing role for HIF-1α." (PMID 30301842, 2018).
tumor (continued). "Further, enhancement of HIF-1α observed in MCF-7 ALDH1A1+ is consistent with the higher tumor growth by the reprogramming of metabolism of tumor cells toward an oxygen-independent biochemical pathway and the sustainment of stemness property in many cancers." (PMID 30541574, 2018). "Hypoxia-activated HIF-1α is also involved in cellular processes controlling phenotypes of stem cells during embryogenesis, as well as in cancer stem cells (CSCs) during tumor initiation and progression." (PMID 29996493, 2018). "Taken together, it is suggested that hypoxic environments, which induce activation of HIF-1α and accumulation of lactate, contribute to evasion of tumor cells from immune system." (PMID 29910728, 2018). "CT exerted its anti‐tumor effect by targeting STAT3/SIRT3/HIF‐1α signaling pathway in vitro and in vivo." (PMID 30094960, 2018). "We observed that targeting HIF1‐α or de novo pyrimidine biosynthesis in combination with gemcitabine strongly reduced the tumor burden in the different mouse models of pancreatic cancer." (PMID 29460395, 2018). "The function of HIF-1α has been extensively investigated in nearly every stage of tumor progression." (PMID 30111297, 2018). "Inhibition of HIF1α activity in DEN–treated WwoxΔHep mice through systemic treatment with digoxin significantly attenuated tumor development suggesting that accelerated HCC development is indeed mediated by increased HIF1α activity." (PMID 30370248, 2018). "As the hypoxic environment is found within the tumour mass, expression of HIF-1α increases in proportion to the size and density of a tumour as well as the tumour stage." (PMID 29914529, 2018). "But in the present study, we investigated the impact of MET NVB and/or Endostar on the frequency of CEPs, expression of CD31, VEGF, and HIF-1α in tumor-bearing mice." (PMID 30305062, 2018). "The level of HIF-1α in tumor cells was significantly higher than that in the control group (P < 0.05)." (PMID 30185231, 2018). "In this scenario, AMPK, as a metabolic tumor suppressor, functions to coordinate glycolytic and oxidative metabolism in proliferating cells by restricting HIF-1α function." (PMID 30258193, 2018). "At the same time, lactic acid released by glycolytic cancer cells into the tumor microenvironment also stabilize HIF-1α expression in bone-marrow derived macrophages." (PMID 30619850, 2018). "The activation of the HIF1α/OATPs signaling axis in cancer cells is responsible for the tumor-specific uptake of heptamethine carbocyanine dyes; thus, tumors can be identified without chemical modification." (PMID 29706843, 2018). "It has been shown that HIF-1α regulated the expression of genes involving angiogenesis, tumor invasion, metastasis, proliferation and apoptosis." (PMID 30355300, 2018). "In our study, 7 days after the administration of DMXAA, an upregulation of HIF-1α level and the number of blood vessels in the tumor were observed what in consequence led to tumor regrowth." (PMID 29743548, 2018). "Inflamed tissues and tumor microenvironment are characterized by limited supplies of oxygen, which provokes the expression of hypoxia-inducible factor 1 alpha (HIF1α)." (PMID 30140167, 2018). "The functionality of HIF-1 as it drives the response of the tumour to hypoxia is determined by the availability of HIF1α, which is up-regulated under hypoxia." (PMID 29098360, 2018).